TRPS1 (transcriptional repressor GATA binding 1)
Diseases named in the same sentence as TRPS1 in open-access papers (continued):
Sharing a sentence is not in itself a finding about the gene and the disease.
dental caries (1 paper, 2022). The decay of a tooth, in which it becomes softened, discolored, and/or porous. "Using the cKO approach with Trps1 deletion only in developed odontoblasts, we focused on investigating the role of Trps1 transcription factor as potential contributor to susceptibility to dental caries." (PMID 35573139, 2022). "Notably, severe tooth misalignments not only increase risk of dental caries but also of periodontal disease, underlining the role of Trps1 not only in formation of sound mineralized dental tissues, but also in the dento-alveolar complex." (PMID 35573139, 2022). "Interestingly, and highly relevant to the development of dental caries, the enamel quality is also impaired by Trps1 deficiency in odontoblasts, as evident from lower enamel microhardness, and some cases of attrition in Trps1Col1a1cKO mice." (PMID 35573139, 2022). "This dynamic expression pattern suggests that Trps1 is involved in odontoblast differentiation and function, hence in dentin formation, suggesting that the susceptibility to dental caries reported in TRPS patients might result from formation of compromised dental mineralized tissues." (PMID 35573139, 2022). "To determine consequences of Trps1 deficiency on quality of dental tissues, which are formed postnatally in mice, and gain insights into the mechanism underlying increased susceptibility to dental caries in TRPS, we generated mice with deficiency of Trps1 in odontoblasts (Trps1Col1a1cKO mice)." (PMID 35573139, 2022). "Cases of hypodontia, abnormal tooth morphogenesis, impaired dentin mineralization, large dental pulp chambers, and extensive dental caries have also been reported, underscoring the clinical importance of TRPS1 for tooth development." (PMID 35573139, 2022). "This project builds upon the clinical findings of high prevalence of dental caries in TRPS patients, as well as data from in vitro studies of Trps1-deficient odontoblast cell line and animal models, which collectively suggest an important role of Trps1 in formation of dentin." (PMID 35573139, 2022).
dental disorders (1 paper, 2012). "Thus, revealing the Trps1 molecular network in odontoblasts will certainly contribute to greater understanding of the molecular mechanisms of dentinogenesis and associated human dental disorders." (PMID 22508542, 2012).
eccrine adenocarcinomas (1 paper, 2023). "Our study demonstrates a very high expression of TRPS1 in eccrine carcinomas other than MAC (88% overall; 81% intermediate to high positive)." (PMID 36810569, 2023).
eccrine tumors (1 paper, 2023). "Although we used a different IHC clone than that in a previous study, our findings show that TRPS1 is possibly not helpful in differentiating malignant eccrine tumors from CMBC." (PMID 36810569, 2023).
endometrial tumors (1 paper, 2023). "Immunohistochemical staining indicated that the expression levels of TRPS1 were significantly lower in endometrial tumors than those in normal tissues, whereas TRPS1 was highly expressed in BC tissues compared to normal tissues." (PMID 37344459, 2023).
endometriosis (1 paper, 2025). The growth of functional endometrial tissue in anatomic sites outside the uterine body. "Through this analysis, we identified 42 genome-wide significant (5 × 10−8) genetic variants significantly associated with endometriosis, 6 of which were not reported previously: ABHD1/2p23.3, TMEM131/2q11.2, XRCC4/5q14.2, PPP1R9A/7q21.3, XKR6/8p23.1, and TRPS1/8p23.3." (PMID 40262193, 2025).
Familial adenomatous polyposis (1 paper, 2023). Familial adenomatous polyposis (FAP) is characterized by the development of hundreds to thousands of adenomas in the rectum and colon during the second decade of life. "Supernumerary teeth have also been reported to be associated with various malformation syndromes, including APC-associated familial adenomatous polyposis (FAP), RUNX2-associated cleidocranial dysplasia, and TRPS1-associated tricho-rhino-phalangeal syndrome." (PMID 36901686, 2023).
hidradenocarcinoma (1 paper, 2023). A carcinoma with apocrine and less often eccrine differentiation, arising from the sweat glands. "Three of our hidradenocarcinomas were high positive, and one case was negative for TRPS1 staining." (PMID 36810569, 2023).
hidradenoma (1 paper, 2023). A benign epithelial neoplasm arising from the sweat glands. "Our study demonstrates a very high (86%) expression of TRPS1 in malignant and benign adnexal tumors that are mainly composed of islands or nodules with polygonal cells, e.g., hidradenomas." (PMID 36810569, 2023). "In this study, a total of nine hidradenoma cases, with eight intermediate to high positive, expressed TRPS1." (PMID 36810569, 2023).
hypophosphatemic rickets (1 paper, 2022). Rickets due to low serum phosphate concentrations, the cause of which can be nutritional or genetic. "While such dentin mineralization defects in hypophosphatemic rickets are caused by systemic phosphate deficiency, our previous studies of Trps1 function in odontoblasts indicate that similar phenotype can be caused by cell autonomous mechanisms." (PMID 35573139, 2022). "Interestingly, Phex is one of the phosphate homeostasis genes regulated by Trps1 in odontoblasts and is also mutated in the most common form of the hypophosphatemic rickets, the X-linked hypophosphatemic rickets." (PMID 35573139, 2022). "Specifically, we demonstrated that expression of several genes involved in phosphate homeostasis and hypophosphatemic rickets is regulated by Trps1 in odontoblasts." (PMID 35573139, 2022).
intestinal neuroendocrine neoplasm (1 paper, 2024). A neoplasm with neuroendocrine differentiation that arises from the small or large intestine. "The remaining two (positive) cases included a case of intestinal neuroendocrine neoplasm with intermediate TRPS1 positivity (histoscore 6) and one case of pancreatic duct origin with weak TRPS1 expression (histoscore 1)." (PMID 39449380, 2024).
invasive breast carcinoma (1 paper, 2024). A carcinoma that infiltrates the breast parenchyma. "The TRPS1-negative case was from a female invasive breast carcinoma of no special type (grade 3 according to the Nottingham histologic score)." (PMID 39449380, 2024).
invasive carcinoma (1 paper, 2025). A carcinoma that is not confined to the epithelium, and has spread to the surrounding stroma. "Additionally, most ER-/PR-/AR+ invasive carcinomas with apocrine differentiation exhibited negative expression of TRPS1 and GATA3." (PMID 40822238, 2025).
invasive ductal carcinoma (1 paper, 2025). "Histopathological examination confirmed invasive ductal carcinoma (grade II) with infiltrative growth, ER/PR/AR positivity (90%), and TRPS1 expression, confirming mammary origin." (PMID 40978063, 2025).
Invasive Lobular Carcinoma (1 paper, 2024). "In contrast, in Invasive Lobular Carcinoma (10–15% of BC), TRPS1 can also act as a tumor suppressor, in this case it’s the loss of TRPS1 that, associated to loss of E-Cadherin, drives tumor growth." (PMID 38702730, 2024).
leiomyoma (1 paper, 2024). A well-circumscribed benign smooth muscle neoplasm characterized by the presence of spindle cells with cigar-shaped nuclei, interlacing fascicles, and a whorled pattern. "TRPS1 expression was consistently observed in DFs (100%; 24/24) and leiomyomas (100%; 8/8)." (PMID 39051323, 2024). "The median H-score for TRPS1 expression was highest in leiomyomas followed by DFs." (PMID 39051323, 2024).
lentivirus infection (1 paper, 2022). Virus diseases caused by the Lentivirus genus. "To test this hypothesis, we established an MDA-MB-231 cell line that stably overexpressed TRPS1 by lentivirus infection and puromycin selection." (PMID 35399640, 2022).
lung diseases (1 paper, 2021). "Further verification was done by qPCR as we tested five differential peak-related genes (Rras2, Ttll12, Ccr3, Ccr6 and Trps1) with known contributions to lung diseases." (PMID 33902609, 2021).
metaplastic breast carcinoma (1 paper, 2025). A group of invasive breast carcinomas characterized by the presence of an adenocarcinomatous component which is admixed with a dominant component that is composed of squamous cells, spindle cells, or mesenchymal cells. "TNBCs and metaplastic breast carcinoma, showed higher positivity of TRPS1, compared with GATA3 and SOX10." (PMID 40025593, 2025). "Concordant with these findings, we noted a considerably higher positivity for TRPS1 in metaplastic breast carcinoma (100%) compared with GATA3 (42.9%) and SOX10 (66.7%)." (PMID 40025593, 2025).
metastatic tumors (1 paper, 2024). "With these limitations in mind, we consider that TRPS1 can be included in a panel of other immunohistochemical markers for the diagnosis of cutaneous metastatic tumors, in the context of adequate clinical information." (PMID 39449380, 2024). "In the present study, we aimed to assess the usefulness of TRPS1 in the diagnosis of cutaneous metastatic tumors by studying a larger patient cohort." (PMID 39449380, 2024). "Further studies, comparing namely the expression of metastatic tumors with their primaries of origin, will shed more light on the significance of TRPS1 expression in metastatic skin tumors, namely its value as a diagnostic and/or prognostic marker." (PMID 39449380, 2024). "In metastatic tumors, TRPS1 expression varied significantly among the cases studied, both in terms of percentage of labeled cells and of staining intensity." (PMID 39449380, 2024). "We studied the immunohistochemical expression of TRPS1 in 72 cutaneous metastatic tumors from the breast (n: 19) and other origins (n: 53) in order to assess its diagnostic usefulness." (PMID 39449380, 2024). "Regarding tumoral pathology, the expression of TRPS1 has been studied in primary tumors of the skin; however, very limited data exist on cutaneous metastatic tumors, as only one study has investigated a small number of such cases." (PMID 39449380, 2024). "Regarding the remaining metastatic tumors of non-breast origin, we found TRPS1 expression in over one-third of all cases, including metastases from the lung, pancreas, kidney, and gynecologic tract." (PMID 39449380, 2024).
multiple sclerosis (1 paper, 2014). A progressive autoimmune disorder affecting the central nervous system resulting in demyelination. "Gene Ontology enrichment analysis revealed that TNFSF10 involved in the biological processes including protein kinase cascades, regulation of signal transduction and apoptosis, and the GPS1 and TRPS1 were primarily enriched in multiple sclerosis." (PMID 24932510, 2014).
neuroendocrine neoplasm (1 paper, 2023). Endocrine tumors, also referred to as neuroendocrine tumors (NETs), are defined by a common phenotype which is characterized by the expression of general markers (neuron specific enolase, chromogranin, synaptophysin) and hormone secretion products. "TRPS1 and INSM1 are sensitive markers for predicted breast and neuroendocrine neoplasms, respectively." (PMID 38041048, 2023).
perineurioma (1 paper, 2024). A usually benign perineurioma not associated with a nerve, arising from the soft tissues. "The two cases of perineuriomas showed an absence of TRPS1 expression." (PMID 39051323, 2024).
porocarcinomas (1 paper, 2023). "In the porocarcinoma group, all six cases demonstrated TRPS1 expression, with five being intermediate to high positive." (PMID 36810569, 2023).
Poroma (1 paper, 2023). A benign adnexal neoplasm composed of EPITHELIAL CELLS. "In this study, the percentage of TRPS1-positive cases was highest in poromas (~90% in total)." (PMID 36810569, 2023).
prostate tumour (1 paper, 2004). "Now, it was found that also EIF3S3 and TRPS1 are coamplified in about 30% of the hormone-refractory prostate tumours." (PMID 14997205, 2004).
respiratory failure (1 paper, 2015). The significant impairment of gas exchange within the lungs resulting in hypoxia, hypercarbia, or both, to the extent that organ tissue perfusion is severely compromised. "It has been shown that Trps1 knockout mice die because of neonatal respiratory failure." (PMID 25886207, 2015).
salivary gland carcinoma (1 paper, 2025). A carcinoma that arises from the major or minor salivary glands. "A recent study showed that approximately 92% of salivary gland carcinoma expressed TRPS1." (PMID 40025593, 2025).
sarcoidosis (1 paper, 2023). Sarcoidosis is a multisystemic disorder of unknown cause characterized by the formation of immune granulomas in involved organs. "Unlike myofibroblasts and ECM fibroblasts which enriched fibroblast activation TFs, such as GLIS1 and TRPS1, only in sarcoidosis, endothelial fibroblasts showed enrichment of FLI1, a fibroblast activation suppressor TF, and GATA2, an endothelial cell TF, strictly in sarcoidosis." (PMID 37576111, 2023).
schizophrenia (1 paper, 2025). A major psychotic disorder characterized by abnormalities in the perception or expression of reality. "For example, TFs SMARCA1, TCF4, and TRPS1 have been confirmed to play crucial roles in schizophrenia, and they have been confirmed to target CRABP1." (PMID 39905509, 2025).
smooth muscle tumor (1 paper, 2024). A benign or malignant myomatous neoplasm arising from smooth muscle. "We assessed TRPS1 immunoreactivity in 135 CMNTUDs, comprising 46 fibrohistiocytic/fibroblastic tumors, 28 vascular tumors, 24 peripheral nerve sheath tumors (PNSTs), 21 tumors of uncertain differentiation, and 16 smooth muscle tumors." (PMID 39051323, 2024).
sweat gland carcinoma (1 paper, 2025). A carcinoma arising from the sweat glands. "For instance, TRPS1 co-expression with neuroendocrine markers(e.g., INSM1, Syn) strongly supports endocrine mucin-producing sweat gland carcinoma (EMPSGC)." (PMID 40969274, 2025).
syringoma (1 paper, 2023). A benign sweat gland neoplasm usually affecting the lower eyelids and upper cheeks. "Although we demonstrate TRPS1 staining in secretory cells and in ductular cell layers, none of our syringomas or MACs were positive for the expression." (PMID 36810569, 2023). "All MAC and syringoma cases were negative for TRPS1 expression." (PMID 36810569, 2023). "In light of the natural TRPS1 expression in normal eccrine glands, we think that negative staining in SGTs other than syringoma and MAC may be due to differential fixation or tissue age." (PMID 36810569, 2023).
trichoblastoma (1 paper, 2023). A benign hair follicle neoplasm with trichoblastic differentiation. "This study demonstrated consistent TRPS1 staining of perifollicular mesenchymal cells and papillary mesenchymal bodies in trichoblastomas and trichoepitheliomas." (PMID 37366800, 2023). "The staining pattern of TRPS1 in normal hair follicles demonstrated a similar pattern to that seen in trichoblastoma and trichoepithelioma." (PMID 37366800, 2023).
Zinc deficiency (1 paper, 2025). A deficiency of the essential metal Zinc; an essential cofactor for many enzymes. "Notably, clinical features linked to TRPS1 dysfunction resemble those observed in individuals with low zinc levels, as zinc deficiency can impair zinc‐dependent proteins, potentially exacerbating the condition by worsening clinical manifestations." (PMID 40756095, 2025).
tumor (61 papers, 2012 to 2026). "In vivo CRISPR-cas9 screening with gRNA against these MRs identified Transcriptional Repressor GATA Binding 1 (TRPS-1) as an essential transcription factor for tumor-associated Treg cells." (PMID 38318526, 2024). "To ascertain an association between TRPS1 expression and chemotherapy sensitivity, we collected and analyzed 109 tumor samples from BC patients undergoing chemotherapy." (PMID 39276941, 2024). "Both Trps1 and Phf1 have tumor suppressor properties, are associated with repressive chromatin and are up-regulated outside WOS." (PMID 35087569, 2021). "This review aims to provide a comprehensive evaluation of TRPS1 expression across various tumor types, highlighting both its diagnostic utility and potential pitfalls that may arise in clinical practice." (PMID 39518009, 2024). "Overexpression of TRPS1 was associated with tumor size and stage." (PMID 37171044, 2023). "In vivo validation of a third hit from the insertional mutagenesis screen, TRPS1, showed that while TRPS1 expression is essential for the survival of mammary epithelial cells, combined loss of TRPS1 and E-cadherin expression resulted in accelerated tumor development." (PMID 34771558, 2021). "Mechanistically, miR-222-3p directly targets the 3′ untranslated region (3′UTR) of the tumor-suppressor TRPS1, reducing its expression." (PMID 40074730, 2025). "On the other hand, it is crucial to acknowledge that there are limited data available regarding TRPS1 positivity in other tumor types." (PMID 38902365, 2025). "Another noteworthy instance was a case featuring matching primary AS and distant metastasis, where we observed a reversed staining pattern, namely TRPS1 negativity for the primary tumor and TRPS1 positivity for the distant metastasis." (PMID 38902365, 2025). "Immunohistochemistry revealed positivity for CK and CD68, scattered Ki-67-positive cells, and TRPS1 positivity, indicating tumor cell infiltration." (PMID 40797399, 2025). "TRPS1 expression was also observed in other tumor types, including carcinoma of Mullerian origin, bladder, and lung, limiting its utility in the differential diagnosis." (PMID 40025593, 2025). "Genetic depletion of TRPS-1 in mice delayed tumor growth by inhibiting infiltration and function of tumor-associated Treg cells, while preserving tolerance in the periphery." (PMID 38318526, 2024). "The integration of TRPS1 into multi-marker panels, coupled with emerging technologies such as next-generation sequencing and multiplex IHC, holds promise for improving tumor classification and guiding personalized treatment decisions." (PMID 39518009, 2024). "To further demonstrate ZEB1 as a downstream target of TRPS1 in tumor cell metastasis, we examined the effects of ZEB1 knockdown on migration, invasion and wound healing of TRPS1-MT cells." (PMID 39307879, 2024). "The combination of MPA and RANKL significantly inhibited tumor apoptosis, but knockdown of TRPS1 suppressed this effect." (PMID 37344459, 2023). "The perifollicular mesenchymal cells immediately adjacent to the TB and TE tumor nests were highlighted by TRPS1 immunostaining." (PMID 37366800, 2023). "The gene expression profile of TRPS1 across all tumor samples and paired normal tissues was detected in GEPIA database." (PMID 37344459, 2023). "Of the 117 evaluable tumour samples, 92 samples (79%; 95% CI 70–85%) showed nuclear staining with TRPS1 IHC in 10 to 100% of tumour cells." (PMID 37012444, 2023). "TRPS1 highlighted a unique staining pattern among the mesenchymal cells surrounding tumor nests in TB and TE, appearing to recapitulate structures of the hair follicle." (PMID 37366800, 2023). "While TB and TE more often stained positively with TRPS1, many BCCs were also weakly positive, and overall, the staining within the tumor nests was inconsistent." (PMID 37366800, 2023). "We found that TRPS1 highlighted perifollicular mesenchymal cells adjacent to the nests of TB and TE tumor cells." (PMID 37366800, 2023).